ACACA (acetyl-CoA carboxylase alpha)
Diseases named in the same sentence as ACACA in open-access papers (continued):
Sharing a sentence is not in itself a finding about the gene and the disease.
epilepsy (1 paper, 2022). A brain disorder characterized by episodes of abnormally increased neuronal discharge resulting in transient episodes of sensory or motor neurological dysfunction, or psychic dysfunction. "LHX1, encoding LIM homeobox protein 1, and ACACA, encoding acetyl-CoA carboxylase, have been proposed as potential candidate genes responsible for neurodevelopmental and epilepsy phenotypes, although there is not sufficient evidence to confirm causality to date." (PMID 35606653, 2022).
Hernia (1 paper, 2021). "ACACA was downregulated in the SH-affected animals indicating the development of an unstable structure of the inguinal ring, which can influence the development of hernia." (PMID 33513662, 2021).
Hyperglycemia (1 paper, 2024). An increased concentration of glucose in the blood. "We found that ATP citrate lyase (ACLY), acetyl-Co-A carboxylase (ACACA) which converts acetyl-CoA into malonyl-CoA, fatty acid synthase (FASN) and acetyl-CoA desaturase (SCD) were increased in normoglycemia in MIC26 KOs but mostly unchanged in hyperglycemia." (PMID 39393820, 2024).
kidney cancer (1 paper, 2024). Primary or metastatic malignant neoplasm involving the kidney. "The research focused on ACACA and kidney cancer has not made significant advancements." (PMID 39239554, 2024).
lung adenocarcinoma (1 paper, 2025). A carcinoma that arises from the lung and is characterized by the presence of malignant glandular epithelial cells. "In vitro experiments, when ACACA was knocked down via siRNAs, lung adenocarcinoma and sarcoma cells exhibited significantly reduced proliferation, invasion, and metastatic ability." (PMID 41169354, 2025). "Single-cell analysis of lung adenocarcinoma revealed that ACACA was expressed predominantly within malignant cells and contributed to an immunosuppressive microenvironment through migration inhibitory factor (MIF) signaling and the extracellular matrix (ECM) remodeling pathway." (PMID 41169354, 2025). "The results indicate that ACACA may drive proliferation and survival of tumor cells in lung adenocarcinoma by modulating multiple oncogenic and metabolic pathways while inhibiting apoptosis and immune responses." (PMID 41169354, 2025). "Obviously, these results suggest that ACACA could serve as potential prognostic and immunotherapeutic biomarker across cancers especially lung adenocarcinoma." (PMID 41169354, 2025).
lung squamous cell carcinoma (1 paper, 2025). "Intriguingly, high ACACA expression was inversely correlated with key immunomodulatory pathways, as evidenced by the suppression of interferon-α responses, the inflammatory signaling cascades, and complement activation, particularly in LGG, SARC, PAAD, and lung squamous cell carcinoma (LUSC)." (PMID 41169354, 2025).
mastitis (1 paper, 2023). Inflammation of breast tissue during lactation or postpartum due to an obstructed duct or infection. "The alpha form of this enzyme is encoded by the gene acetyl-CoA carboxylase alpha (ACACA) on BTA19, and QTL for fatty acid composition and somatic cell score (a proxy phenotype for mastitis) have been mapped to this locus." (PMID 36899768, 2023).
mesothelioma (1 paper, 2025). A usually malignant and aggressive neoplasm of the mesothelium which is often associated with exposure to asbestos. "Integrated analysis revealed that ACACA transcript levels were significantly correlated with adverse prognostic indices, with elevated hazard ratios (HRs) for OS, DSS, DFI, and PFI in several tumor types, including LIHC, adrenocortical carcinoma (ACC), mesothelioma (MESO), and uveal melanoma (UVM)." (PMID 41169354, 2025).
neuroblastoma (1 paper, 2021). Neuroblastoma (NB) is the most common solid, extracranial childhood tumor. "Our analysis showed that high levels of both ACACA and FASN correlate with reduced survival in three neuroblastoma patient cohorts covering all five INSS stages and with similar proportion of MYCN-amplification." (PMID 33659885, 2021). "Using five small molecule inhibitors targeting ACACA or FASN and siRNA targeting FASN, we show that inhibition of fatty acid synthesis decreases cell proliferation, reduces MYCN or c-MYC protein levels, and results in neural differentiation in neuroblastoma." (PMID 33659885, 2021). "Collectively, these data suggest that although high expression of both ACACA and FASN consistently correlates to reduced survival in tumors independently of their MYCN status, FASN seems to be a better prognosis marker candidate for neuroblastoma patients." (PMID 33659885, 2021).
nutritional deficiency (1 paper, 2021). "Furthermore, results of the recent studies suggest that the genes involved in hepatic lipid synthesis (ACACA, FASN, LPL, SCD1, FADS1, and FADS2) were down-regulated over nutritional deficiency." (PMID 35111749, 2021).
pregnancy toxemia (1 paper, 2025). "PCR-DNA sequence analysis revealed that the amplified fragments of IL-6 (627 bp), IL-8 (264 bp), FASN (381 bp), SOD3 (393 bp), HMOX1 (460 bp), and ACACA (477 bp) differed between healthy goats and those affected by pregnancy toxemia (PT)." (PMID 41012815, 2025).
triple-negative breast carcinoma (1 paper, 2023). An invasive breast carcinoma which is negative for expression of estrogen receptor (ER), progesterone receptor (PR), and human epidermal growth factor receptor 2 (HER2). "Here, we demonstrate that NFYAv1, a long-form variant, upregulates the transcription of essential lipogenic enzymes ACACA and FASN to enhance the malignant behavior of triple-negative breast cancer (TNBC)." (PMID 37268670, 2023).
type 1 diabetes (1 paper, 2022). "Variants in ACACA have not previously been associated with type 1 diabetes." (PMID 35304577, 2022).
cancer (63 papers, 2012 to 2025). A tumor composed of atypical neoplastic, often pleomorphic cells that invade other tissues. "High ACACA expression was associated with poor survival in various cancers, particularly those exhibiting dysregulated lipid metabolism." (PMID 41169354, 2025). "ACACA encodes an enzyme that facilitates the conversion of acetyl-CoA to malonyl-CoA, promoting lipid synthesis, and is often upregulated in various cancers, including HCC." (PMID 40069732, 2025). "To further comprehend the role of ACACA mutation in pan-cancer, we assessed the association of ACACA expression with tumor mutation burden (TMB) and microsatellite instability (MSI)." (PMID 38584256, 2024). "Previous reports showed that the mutation of ACACA gene was associated with the survival durations in cancers." (PMID 38584256, 2024). "ND-630, a compound known to inhibit ACACA or Acetyl-CoA carboxylase alpha, an enzyme that plays a crucial role in fatty acid synthesis and has been associated with various cancers." (PMID 38049827, 2023). "Moreover, earlier studies have confirmed the essential enzyme ACACA, associated with FA synthesis, is increased in various cancer tissues, and its elevated levels can significantly enhance cell proliferation." (PMID 40069732, 2025). "Then genomic variant analysis of ACACA showed that ACACA variants are ubiquitous in pan-cancer." (PMID 38584256, 2024). "Importantly, MYC has been implicated as a mediator of both RAS and BCR-ABL-driven cancers and is shown to directly influence gene expression of ACACA, FASN, and SCD." (PMID 34399819, 2021). "For instance, acetyl-CoA carboxylase alpha (ACACA) overexpression associates with increased cancer risk and can be detected in early-stage BC, while fatty acid synthase (FASN) promoted BC metastasis and was proposed as a potential therapeutic target for BC treatment." (PMID 34572770, 2021). "Our preliminary immunohistochemical analysis showed that that AT+AA genotypes of rs11871275 were significantly associated with higher expression level of ACACA when compared to TT genotype, which is in line with notion that elevated ACACA expression promotes the proliferation of cancer cells." (PMID 25826294, 2015). "In this study, we utilized a multi-omic approach to amalgamate publicly accessible expression and survival data from cancer patients, thereby profiling the ACACA expression landscape." (PMID 41169354, 2025). "Specifically, genes like LRP, ACACA, and ACSM are linked to the altered metabolism of cancer cells, which promotes their proliferation, survival, and ability to withstand genotoxic stress." (PMID 40225267, 2025). "The comprehensive multiomics profiling and immunological implications of ACACA across various cancer types have yet to be fully elucidated." (PMID 41169354, 2025). "In conclusion, our study elucidates a comprehensive role of ACACA across cancers, not only as a canonical lipogenic enzyme but also dynamic regulator of the cancer ecosystem that integrates metabolic flux with immune evasion and stromal remodeling." (PMID 41169354, 2025). "Although targeting ACACA inhibits tumor growth and increases apoptosis, it also induces different cell states in cancer cells by activating survival pathways." (PMID 40066226, 2025). "We performed a comprehensive pan-cancer analysis of ACACA via transcriptomic, proteomic, and clinical data from The Cancer Genome Atlas (TCGA), Clinical Proteomic Tumor Analysis Consortium (CPTAC), and the Human Protein Atlas (HPA) databases." (PMID 41169354, 2025). "Collectively, these findings imply that ACACA potentially has a multifaceted role in orchestrating energy balance, modulating immune responses, and driving cancer progression." (PMID 41169354, 2025). "ACACA serves as a key metabolic regulator for proteins, lipids, and carbohydrates, and is heavily involved in reprogramming various metabolic pathways in cancer cells." (PMID 40648712, 2025).
cancer (continued). "Integrated RNA sequencing analysis of TCGA cancer specimens and Genotype-Tissue Expression (GTEx) normal controls confirmed consistent upregulation of ACACA in diverse tumors." (PMID 41169354, 2025). "Alternative splicing of ACACA can produce isoforms with altered enzymatic activity, which contribute to dysregulated lipid metabolism in cancer cells." (PMID 40225267, 2025). "In order to elucidate the interplay between ACACA-driven lipid metabolism and immune checkpoint regulation, we performed correlation analyses across 33 cancer types." (PMID 41169354, 2025). "Bioinformatic analyses revealed the significant influence of ACACA on cell proliferation across a variety of malignant tumors." (PMID 41169354, 2025). "Key enzymes such as hexokinase 2 (HK2), pyruvate kinase M1/2 (PKM), and acetyl-CoA carboxylase alpha (ACACA) were highlighted, reflecting the metabolic reprogramming often observed in cancer cells, known as the Warburg effect." (PMID 40678800, 2025). "The investigation revealed that the reduced growth of cancer cells resulted from the inhibition of lipid metabolism, via the downregulation of Acetyl-CoA Carboxylase 1 (ACACA)." (PMID 39195369, 2024). "The cell lines belonging to the M subgroup exhibited notable reliance on cancer metabolic genes such as ACACA, the pivotal player of mtFAS." (PMID 39300154, 2024). "Here, the established model proved that ACACA expression was obviously increased in various cancers." (PMID 38584256, 2024). "Specially, by the in vivo and in vitro experiments, we proved that ACACA, a rate-limiting enzyme of FA metabolism, govern cancer stemness and immune escape and promote cancer progression." (PMID 38584256, 2024). "A strong interaction between cancer stem cells (CSCs) with high expression of ACACA and macrophages through CD74 molecule (CD74) and integrin subunit beta 1 (ITGB1) signaling was identified." (PMID 38584256, 2024). "The expression of ACACA presented a positive correlation with TMB in most cancers, including LIHC, while it was negatively correlated with BRCA and ESCA." (PMID 38584256, 2024). "An exquisite mechanism is observed in cancer cells during hypoxia to promote the expression of lipogenic genes acetyl-CoA carboxylase alpha (ACACA) and fatty acid synthase (FASN), by mean of the acetate mediated histone H3 acetylation." (PMID 37404756, 2023). "ACACA is involved in many cancer metabolism reprogramming processes, as cancer cells depend on fatty acids for membrane synthesis." (PMID 38049827, 2023). "Extensive evidence has shown that overexpression of ACACA is essential for proliferation and invasion and promoting glucose-mediated fatty acid synthesis in many human cancers." (PMID 38049827, 2023). "SREBP-1 is a key molecule in regulating the production of fatty acids and triglycerides through stimulating the expression of FASN and ACACA, which increases cancer cell viability and promotes tumor growth." (PMID 36496421, 2022). "For example, some genes in the module, such as aldehyde dehydrogenase (ALDH2) and acetyl-CoA carboxylase (ACACA), are known oncogenes, promoting cancer stem cell formation and drug resistance." (PMID 34159316, 2021). "MYC promotes metabolic reprogramming in cancer and is involved in lipogenesis by pronouncedly activating acetyl-CoA carboxylase (ACACA), fatty acid synthetase (FASN), and stearoyl-CoA desaturase (SCD)." (PMID 33791309, 2021). "We analyzed the expression of five major DNFA enzymes SCD, FASN, ACLY, ACSS2 and ACACA using RNA-Seq data from 30 diverse cancer types in The Cancer Genome Atlas (TCGA)." (PMID 31316083, 2019). "We found that high expression of SCD, FASN and ACACA significantly correlates with poor prognosis in all cancers considered collectively." (PMID 31316083, 2019). "We discovered that genetic depletion of acetyl-CoA carboxylase (ACACA or ACC1) or ATP citrate lyase (ACLY) protected cancer cells from hypoxia-induced apoptosis." (PMID 26452058, 2015).
cancer (continued). "Soraphen A is a highly potent inhibitor of ACACA, hence it blocks de novo lipid synthesis and induces apoptosis in cancer cells." (PMID 25215509, 2014). "Our study establishes ACACA as a key metabolic regulator that links lipid metabolism to immune evasion and drug resistance, highlighting its potential as a promising therapeutic target across cancers." (PMID 41169354, 2025). "To fully assess the role of ACACA across cancers, we employed bioinformatic techniques to analyze ACACA expression data across several cancer databases, including The Cancer Genome Atlas (TCGA), Cancer Cell Line Encyclopedia (CCLE), and Clinical Proteomic Tumor Analysis Consortium (CPTAC)." (PMID 41169354, 2025). "Interestingly, analysis of the Depmap dataset shows that SCD dependency inversely correlates with the expression levels of both FASN and ACACA (ACC) across all cancer cells lines and particularly AML ones." (PMID 39187579, 2024). "Furthermore, inhibition of FASN and ACACA leads to apoptosis in cancer cells, whereas the addition of exogenous fatty acids restored normal cell growth." (PMID 39457100, 2024). "Knockdown of ACACA by siRNA also resulted in a reduction in product-to-substrate ratio in human lung fibroblasts, suggesting that ACACA activity was attenuated in lung fibroblasts by primary cancer." (PMID 36607556, 2023). "Many studies have indicated that ACACA is a potential target for cancer treatment 15-21." (PMID 33391420, 2021). "However, studies found that malignant tumors had a strong capability for fatty acids synthesis, that ACACA was overexpressed in malignant cancers, and that the inhibition of ACACA resulted in cell-cycle arrest and apoptosis of cancer cells." (PMID 31920968, 2019). "We and other groups also found that either the imbalanced circulating cholesterol or upregulated expression of FASN, ACACA and SREBPs correlated with a poorer diagnosis in different cancers, implying a significance of the lipid metabolism during the cancer development in clinic." (PMID 31416244, 2019). "In addition, ACACA is also known to be upregulated and support the proliferation of many cancers including breast, colon, lung, and liver." (PMID 24958265, 2013). "However, the multiomics investigation and immunological implications of ACACA across cancers remain unclear." (PMID 41169354, 2025). "Note that the highly prioritized acetyl-CoA conversion by ACACA, leading to the activation of fatty acid synthesis is only evident when looking at the non-mitochondrial version of the pathway, since all alternative conversion branches from acetyl-CoA are downregulated in the cancer cells." (PMID 36282866, 2022). "Additionally, ACACA is upregulated in multiple types of human cancers; therefore, ACACA may also contribute to cell survival in Bcl-xL-overexpressing tumor cells." (PMID 22480302, 2012). "Through differential splicing, genes such as ACACA, ACSM, and LRP contribute to the altered metabolic pathways in cancer." (PMID 40225267, 2025). "To delineate the oncogenic networks modulated by ACACA, we performed GSEA on transcriptomic datasets spanning 33 TCGA cancer types, by stratifying patients into high (top 25%) and low (bottom 25%) ACACA expression cohorts." (PMID 41169354, 2025). "FASN, ACACA, ACLY, and ACSL4 are considered key enzymes in lipid metabolism, and previous studies have shown that they can promote the proliferation of various cancers." (PMID 39891099, 2025). "These cancer cells develop de novo FA synthesis with increased activity of multiple lipogenic enzymes, ACC, ACLY, CoA carboxylase (ACACA), and SCD." (PMID 39332525, 2024). "Cancer cells activate lipogenic enzymes, including ATP-citrate lyase (ACLY), acetyl-CoA carboxylase (ACC), CoA carboxylase (ACACA), fatty acid synthase (FASN), and SCD, resulting in increased production of fatty acids." (PMID 38765144, 2024).